CENPBD1P (CENPB DNA-binding domain containing 1, pseudogene)
Synonyms: MGC16385; formerly CENPBD1
Gene: Transcribed unitary pseudogene on chromosome 16 (89,969,983 to 89,971,922, reverse strand). Ensembl gene ENSG00000177946.
Subcellular location: Nucleus